IL9R (interleukin 9 receptor)
Description:
Plays an important role in the immune response against parasites by acting as a receptor of IL9.
Synonyms: IL-9R; CD129
Tractability: Antibody: its Gene Ontology location is reachable by antibodies, with high confidence; UniProt places it where antibodies can reach, with medium confidence; UniProt predicts a signal peptide or a membrane-spanning region. PROTAC: ubiquitination databases record sites on it.
Gene: Protein-coding gene on chromosome X (155,997,696 to 156,013,017, forward strand). Ensembl gene ENSG00000124334.
Subcellular location: Cell membrane; Secreted
Pathways (Reactome):
Immune System: Interleukin-9 signaling
Gene Ontology:
Molecular function: interleukin-9 receptor activity; interleukin-9 binding; cytokine receptor activity
Biological process: interleukin-9-mediated signaling pathway; immunoglobulin mediated immune response; regulation of cell population proliferation; signal transduction; cytokine-mediated signaling pathway
Cellular component: plasma membrane; external side of plasma membrane; extracellular region; membrane
Homologues: Orthologues: macaque IL9R (89% identical), pig IL9R (59% identical), rabbit IL9R (58% identical), guinea pig IL9R (56% identical), mouse Il9r (52% identical), rat Il9r (50% identical), zebrafish mpl (12% identical). Paralogues in human: IL2RB (19% identical), IL4R (17% identical), IL21R (17% identical), EPOR (14% identical), CSF2RB (13% identical), IL7R (11% identical), MPL (11% identical).
Diseases named in the same sentence as IL9R in open-access papers:
IL9R is named in the same sentence as 50 diseases in open-access papers, as found by Europe PMC text mining. Sharing a sentence is not in itself a finding about the gene and the disease. The quoted sentences say what the papers report.
asthma (7 papers, 2013 to 2024). "The most precise role of IL-9 was found to be associated with human allergic inflammation, both IL-9 and IL-9R was found to be genetically linked to human asthma." (PMID 31164892, 2019). "IL-9 found to be associated with human conditions, such as allergy and asthma, as both IL-9 and IL-9R found to have genetic association with human asthma." (PMID 31164892, 2019). "Nonetheless, the genetic association studies identified the association of IL-9 and IL-9R with human asthma, which was further validated in mouse model of allergic inflammation in asthma." (PMID 29867972, 2018). "IL-9 is known to play crucial role in allergic inflammation in asthma as both IL-9 and IL-9R were shown to be genetically associated with the disease." (PMID 28993609, 2017). "The authors showed that a IL9R allele – sDF2*10 – was more likely to be transmitted among patients with asthma and was found homozygotic among asthma patients more often than expected." (PMID 24260251, 2013). "Both IL-9 and IL-9R polymorphism are found to be genetically associated with asthma." (PMID 29867972, 2018). "In addition, elevated mRNA expression levels of IL-9 and IL-9 receptor (IL-9R) were detected in patients with asthma." (PMID 39175819, 2024). "In patients with asthma, IL-9R is expressed by both lung mast and polymorphonuclear cells." (PMID 28187441, 2017).
Allergy (4 papers, 2017 to 2025). An allergy is an immune response or reaction to substances that are usually not harmful. "We found that the absence of IL-9R signalling conferred resistance to both infection and allergy, as indicated by the reduced fungal load and decreased inflammatory lung pathology in infection as well as in ABPA." (PMID 28090087, 2017).
psoriasis (4 papers, 2013 to 2025). An autoimmune condition characterized by red, well-delineated plaques with silvery scales that are usually on the extensor surfaces and scalp. "Collectively, both patients with psoriasis and psoriatic animal models show an excessive expression of IL-9 and IL-9R and an altered frequency of Th9 cells, suggesting that IL-9 promotes psoriasis and PsA development." (PMID 40771819, 2025). "IL-9R expression was increased in the dermis—particularly at the dermal–epidermal junction—in patients with psoriasis." (PMID 40771819, 2025). "Among skin diseases, it was reported that the patient’s skin with psoriasis expressed a higher number of IL-9R–positive cells and the patient’s skin with atopic dermatitis expressed higher IL-9 mRNA compared with the normal skin." (PMID 37398641, 2023). "In K5.hTGF-β1 transgenic mice, exhibiting a psoriasis-like phenotype, we found increased IL-9R and IL-9 expression in the skin and intradermal IL-9 injection induced Th17-related inflammation." (PMID 23335955, 2013). "Similarly, K5.hTGF-β1 transgenic (psoriasis-prone) mice exhibited a higher expression of IL-9 and IL-9R in the skin compared to control mice." (PMID 40771819, 2025). "The involvement of IL-9 in human autoimmunity has been studied in psoriasis, where it was shown that IL-9 receptor (IL-9R) is increased in lesioned compared to healthy skin, and in lupus erythematous, where IL-9 was reported to be highly expressed in the serum." (PMID 32375811, 2020). "In addition, we observed that IL-9R expression in lesional skin from psoriasis patients was markedly higher than in healthy skin from control subjects." (PMID 23335955, 2013). "In addition, we studied IL-9R expression in psoriatic skin lesions and on CD4+ T cells and the effect of IL-9 on IL-17A production in cultured human peripheral blood mononuclear cells or CD4+ T cells from psoriasis patients." (PMID 23335955, 2013).
lymphoma (3 papers, 2014 to 2016). A malignant (clonal) proliferation of B- lymphocytes or T- lymphocytes which involves the lymph nodes, bone marrow and/or extranodal sites. "IL-9R was expressed in both mRNA and protein levels in the five lymphoma cell lines, including LY1, LY8, MINO, SP53 and Jurkat." (PMID 27364124, 2016). "Concordant with in vivo observations, the expression of IL-9R in lymphoma cell-lines was confirmed by RT-PCR and western blot analysis, respectively." (PMID 27364124, 2016). "IL-9R expression was demonstrated for both mRNA and protein levels within the five lymphoma cell-lines, including LY1, LY8, MINO, SP53 and Jurkat." (PMID 27364124, 2016). "In addition, deletion of IL9R may affect JAK-STAT signaling in response to IL9, which is another pathway important in normal B cells and lymphomas." (PMID 25123191, 2014).
Autoimmunity (2 papers, 2018 to 2020). The occurrence of an immune reaction against the organism's own cells or tissues. "Moreover, IL-9R-deficient mice immunized with MOG develops severe EAE and Tregs isolated from IL-9R-deficient animals were shown to have poor suppressive function, suggesting that IL-9 regulates Tregs suppressive functions in autoimmunity." (PMID 29867972, 2018).
Azoospermia (2 papers, 2019 to 2020). Absence of any measurable level of sperm,whereby spermatozoa cannot be observed even after centrifugation of the semen pellet. "Deletion of IL9R or other adjacent loci in the long-arm pseudoautosomal region might be responsible for some phenotypic features associated with Yq deletions, such as short stature, azoospermia, learning disabilities, and facial dysmorphism." (PMID 33344636, 2020). "It was speculated that the deletion of IL9R or other adjacent loci in the long-arm pseudoautosomal region might be responsible for some phenotypic features associated with Yq deletions, such as short stature, azoospermia, learning disabilities, and facial dysmorphism." (PMID 31828149, 2019).
breast carcinoma (2 papers, 2020 to 2023). "Concerning protein expression in cancer, IL9R significantly enriched in endometrial cancer compared to renal cancer, breast cancer, and other malignancies." (PMID 33329510, 2020). "Because 4T1 breast cancer cells did not express IL9R on their surface, the therapeutic effect of IL9 therapy on macrophage-enriched 4T1 breast cancer was also evaluated." (PMID 36968220, 2023).
carotid atherosclerosis (2 papers, 2013). A thickening and loss of elasticity of the walls of carotid arteries that occur with formation of atherosclerotic plaques. "Here we have examined IL-9 and IL-9 receptor (IL-9R) systemically and locally in patients with coronary and carotid atherosclerosis." (PMID 24023645, 2013). "Carotid lesion samples from patients with asymptomatic and symptomatic carotid atherosclerosis had markedly increased expression of IL-9 and IL-9R as compared with samples from non-atherosclerotic vessels (common iliac artery)." (PMID 24023645, 2013).
colitis (2 papers, 2018 to 2021). Inflammation of the colon. "In oxazolone-mediated colitis model also there was an increase in the expression of IL-9 and IL-9R by intestinal epithelial cells." (PMID 29881387, 2018). "Moreover, abundant IL-9R expressing intestinal epithelial cells were observed in the gut mucosa of UC patients indicating the role of IL-9 and Th9 cells in promoting colitis." (PMID 29881387, 2018). "Several genes such as Gata3, Itk, Ccl8, Ccl22, Ccr4, Crlf2, Il9r, Il1rl1, and Arg2 are regulated concordantly in T-cell transfer colitis, acute DSS colitis and the time point representing high inflammation in the DSS time course." (PMID 34136502, 2021).
colorectal cancer (2 papers, 2021 to 2022). A primary or metastatic malignant neoplasm that affects the colon or rectum. "Th9 cells promote the expansion of CD8+ T cells in an IL-9R-dependent manner in colorectal cancer." (PMID 33816497, 2021).
diffuse large B-cell lymphoma (2 papers, 2014 to 2021). "IL-9R was markedly overexpressed in diffuse large B-cell lymphoma tissues compared to their counterparts, and it was associated with several adverse prognostic parameters." (PMID 24722378, 2014). "Wang and colleagues reported elevated serum levels of IL-9 in B cells from non-Hodgkin’s lymphoma and diffuse large B-cell lymphoma (DLBCL) patients, along with high levels of IL-9R expression in tumoral tissues that correlate with adverse prognostic markers of the disease." (PMID 34944921, 2021).
Hodgkins lymphoma (2 papers, 2018 to 2022). A heterogeneous group of malignant lymphoid neoplasms of B-cell origin characterized histologically by the presence of Hodgkin and Reed-Sternberg (HRS) cells in the vast majority of cases. "In agreement with our data, IL9R has been associated with different inflammatory, autoimmune, and malignant diseases, such as psoriasis lesion, lupus erythematous, and various human leukemias, including T-cell leukemia, megakaryoblastic leukemia, and Hodgkin lymphomas." (PMID 29937515, 2018).
lung carcinoma (2 papers, 2022). "Lastly, elevated expression of IL-9R and Arg1 in tumor lesions is associated with poor prognosis in lung cancer patients." (PMID 35778404, 2022). "High expression of IL9 and IL9R clearly associated with poor survival probability in lung cancer patients." (PMID 35778404, 2022). "Multiplex-immunohistochemistry was performed to confirm that TAMs in lung cancer patients express IL-9R at the protein level." (PMID 35778404, 2022). "Consistent with the data from lung cancer patients, lung macrophages occupied over 75% of the IL-9R+ cells." (PMID 35778404, 2022). "Finally, we performed FACS analysis in the human adenocarcinoma lung cancer cell line A549 to understand if IL-9R is expressed in these tumor cells and detected IL9R expression in A549 cells." (PMID 35514957, 2022). "Thus, blocking IL-9 signaling on lung macrophages, when macrophages are IL-9R+, could be a feasible therapeutic strategy for lung cancer and potentially other lung diseases." (PMID 35778404, 2022).
melanoma (2 papers, 2022 to 2023). A malignant, usually aggressive tumor composed of atypical, neoplastic melanocytes. "Seven days after B16 melanoma injection, mice were treated with nanoparticles containing either Scrambled (Scr)-siRNA or Il9r-siRNA every 72hs." (PMID 35778404, 2022). "Because the B16F10 melanoma cells did not express IL9R on their surface, autocrine IL9 expression did not affect the in vitro proliferation of IL9-B16F10 cells." (PMID 36968220, 2023).
rheumatoid arthritis (2 papers, 2019 to 2021). A chronic, systemic autoimmune disorder characterized by inflammation in the synovial membranes and articular surfaces. "In rheumatoid arthritis (RA), an increased expression of IL-9 and IL-9R is observed in synovial tissue, which also correlates with the degree of tissue inflammation." (PMID 31035677, 2019). "Indeed, high serum levels of IL-9 and soluble IL-9R have been found in rheumatoid arthritis (RA) patients." (PMID 33995403, 2021). "Relative mRNA expression of PU.1, IL-9, IL-17 and IL-9R in control conditions (Th0), Th9- and Th17-inducing conditions in naive and non-naive T cells of healthy donors (HD) and rheumatoid arthritis (RA) patients." (PMID 33995403, 2021).
systemic sclerosis (2 papers, 2018 to 2024). A chronic disorder, possibly autoimmune, marked by excessive production of collagen which results in hardening and thickening of body tissues. "Recently, neutrophils isolated from patients with systemic sclerosis (SSc) express IL-9R and exposure of these neutrophils to rIL-9 can significantly induce NET formation." (PMID 30622982, 2018).
anaphylaxis (1 paper, 2012). An acute hypersensitivity reaction that occurs from exposure to an allergen. "Deficiency in IL-9 or IL-9R attenuates intestinal anaphylaxis, while transgenic expression of IL-9 in the intestine results in local mastocytosis and increased susceptibility to intestinal anaphylaxis." (PMID 22413008, 2012).
anaplastic large cell lymphoma (1 paper, 2022). Anaplastic large cell lymphoma (ALCL) is a rare and aggressive peripheral T-cell non-Hodgkin lymphoma, belonging to the group of CD30-positive lymphoproliferative disorders, which affects lymph nodes and extranodal sites. "The dysregulation of IL-9 and IL-9R could be detected in the biopsy specimens and serum of patients with HL, anaplastic large cell lymphoma (ALCL), and nasal NK/T cell lymphoma." (PMID 35211408, 2022).
atherosclerosis (1 paper, 2013). A disease characterized by the build-up of fatty material and calcium deposition in the arterial wall resulting in partial or complete occlusion of the arterial lumen. "This suggests a role for the IL-9/IL-9R interaction in atherosclerosis, but the functional consequences of these findings are at present unclear." (PMID 24023645, 2013).
autoimmune disease (1 paper, 2022). A disorder resulting from loss of function or tissue destruction of an organ or multiple organs, arising from humoral or cellular immune responses of the individual to their own tissue constituents. "IL9R is a receptor of interleukin 9 (IL-9), which participates in various models of T cell-dependent inflammation and plays an important role in driving the immune responses to autoimmune diseases and chronic inflammation on mucosal surfaces." (PMID 36118358, 2022).
coronary atherosclerosis (1 paper, 2013). Atherosclerosis of the coronary vasculature. "Here we report for the first time increased levels of both IL-9 and IL-9R in patients with carotid and coronary atherosclerosis." (PMID 24023645, 2013). "We examined this hypothesis by various experimental approaches including studies on the expression of IL-9 and IL-9R in patients with carotid and coronary atherosclerosis." (PMID 24023645, 2013).
endometrial cancer (1 paper, 2020). Primary or metastatic malignant neoplasm involving the endometrium (mucous membrane that lines the endometrial cavity). "Similar to IL9, IL9R RNA was also up-regulated in endometrial cancer tissues (UCEC) compared to adjacent normal tissues (n = 265, p < 0.05)." (PMID 33329510, 2020). "Firstly, IL9R RNA was found not relevant to the DFS or OS of endometrial cancer based on a small sample size of data(n = 168) from the TCGA dataset." (PMID 33329510, 2020). "Besides, IL9R, the receptor of IL9, was up-regulated in the endometrium tissue and endometrial cancer tissues as well." (PMID 33329510, 2020).
inflammatory bowel disease (1 paper, 2018). A spectrum of small and large bowel inflammatory diseases of unknown etiology. "In the gut inflammation in inflammatory bowel diseases (IBD), IL-9-producing CD4+ T cells were found to be colitogenic, as gut epithelial cells of ulcerative colitis patients expressed elevated levels of IL-9R." (PMID 29867972, 2018).
Insulin resistance (1 paper, 2025). Increased resistance towards insulin, that is, diminished effectiveness of insulin in reducing blood glucose levels. "To better understand how IL-9 might affect the pathogenesis of diet-induced obesity and insulin resistance, we used mice deficient in IL-9/IL-9R signaling." (PMID 40962954, 2025).
lung adenocarcinoma (1 paper, 2022). A carcinoma that arises from the lung and is characterized by the presence of malignant glandular epithelial cells. "The expression of IL-9R on lung adenocarcinoma cells may permit direct effects of IL-9 on tumor cell proliferation or apoptosis." (PMID 35514957, 2022). "Moreover, our findings demonstrate that anti-IL-9 antibodies markedly suppress tumor growth in vivo and identify IL-9R+ TILs and lung adenocarcinoma cells as targets for IL-9 signaling." (PMID 35514957, 2022). "In summary, subsets of tumor infiltrating lymphocytes in the lung as well as lung adenocarcinoma cells express IL9R and may thus be targets for immunomodulatory and cancer promoting effects of IL-9." (PMID 35514957, 2022).
lupus erythematosus (1 paper, 2022). An autoimmune, connective tissue chronic inflammatory disorder affecting the skin, joints, kidneys, lungs, heart, and the peripheral blood cells. "Previous studies have shown enhanced serum levels of IL-9R in autoimmune conditions (i.e., lupus erythematosus)." (PMID 35204724, 2022).
malaria (1 paper, 2025). Malaria is a serious and sometimes fatal disease caused by a parasite that commonly infects a certain type of mosquito which feeds on humans. "Despite mining numerous publicly available human malaria datasets, we were unable to find a high IL-9R-expressing B cell population that could be correlated with enhanced protection upon pathogen re-exposure." (PMID 40215168, 2025).
multiple sclerosis (1 paper, 2022). A progressive autoimmune disorder affecting the central nervous system resulting in demyelination. "Previous studies have shown IL-9 affects microglia in multiple sclerosis, and IL-9R expression has been detected in human blood monocytes and alveolar macrophages." (PMID 35778404, 2022).
Obesity (1 paper, 2025). Accumulation of substantial excess body fat. "Taken together, during obesity, IL-9 production by CD4 + T cells and ILC2s and IL-9R expression on macrophages are significantly downregulated." (PMID 40962954, 2025). "During diet-induced obesity in mice, the frequencies of IL-9 + CD4 + T cells and ILC2s and IL-9R expression on macrophages are significantly decreased." (PMID 40962954, 2025). "Furthermore, in vivo macrophage depletion resulted in increased frequencies of ILC2s and eosinophils in the adipose tissue of HFD-fed IL-9R KO mice compared with PBS-treated controls, indicating that macrophages are the major target cell types of IL-9 during obesity." (PMID 40962954, 2025).